TNF (tumor necrosis factor)
Diseases named in the same sentence as TNF in open-access papers (continued):
Sharing a sentence is not in itself a finding about the gene and the disease.
diabetes (continued). "Furthermore, in patients with diabetes, infection with SARS-CoV-2 induces a more pronounced inflammatory response due to the excessive production of interleukins—specifically interleukin-6 (IL-6), interleukin-8 (IL-8), and tumor necrosis factor-α (TNF-α)." (PMID 40861049, 2025). "Moreover, they showed higher values of glycemic (FPG and HbA1c) and inflammatory (CRP, TNF-alpha, and ESR) markers, as well as a lower GFR, and higher prevalence of hypertension, diabetes mellitus, ischemic heart disease, heart failure, peripheral artery disease, and stroke." (PMID 41106480, 2025). "CGA has been shown to modulate the production of inflammatory mediators such as TNF-α, IL-1β, IL-6, IL-8, NO, and PGE2, and regulate key signaling pathways such as NF-κB, MAPK, and Nrf2, providing protective effects against cardiovascular disease and diabetes mellitus." (PMID 40943313, 2025). "Beyond TNF-α inhibitors, other immunosuppressive agents (e.g., corticosteroids, calcineurin inhibitors, and antimetabolites) or conditions like severe neutropenia, advanced HIV, or uncontrolled diabetes can similarly obscure typical inflammatory responses and delay diagnosis of severe infections." (PMID 40821270, 2025). "Moreover, they showed higher values of glycemic (FPG and HbA1c) and inflammatory (CRP, TNF-alpha, and ESR) markers, as well as a lower GFR, lower levels of HDL cholesterol, and a higher prevalence of hypertension, diabetes mellitus, ischemic heart disease, peripheral artery disease, and cancer." (PMID 41106480, 2025). "For example, in HaCaT cells, a cell line derived from human skin epithelial cells, incubation under hyperglycemic conditions did not affect AQP3 expression; however, treatment with TNF-α, the corneal expression of which we found to be increased with diabetes in mice in vivo, decreased AQP3 levels." (PMID 41369370, 2025). "Although there were correlations between cognitive performance and various cognitive scores, mediator analysis results indicated that the biomarkers IL‐6, MDA, NSE, VCAM‐1, and TNF‐α did not play a mediating role in the neuropathology of diabetes‐related cognitive impairment." (PMID 39829127, 2025). "In the current study, participants with hypertension, hyperlipidaemia, diabetes, and history of statin and calcium channel blocker use had significantly higher TNF-α levels compared to participants without these health conditions indicating an increased level of inflammation." (PMID 39186241, 2024). "However, previous clinical studies suggested that targeting TNF-α or the TNF-α receptor alone was not sufficient to improve glycemic control in diabetes." (PMID 38672413, 2024). "Notably, patients with American cutaneous leishmaniasis (ACL—20.17 ± 1.63 pg/mL), patients with type 2 diabetes mellitus (T2DM—23.60 ± 7.29 pg/mL), and patients with both diseases (23.53 ± 3.22 pg/mL) exhibited higher TNF-α levels compared to the control group (10.20 ± 2.67 pg/mL)." (PMID 39199338, 2024). "Additionally, TNF‐α level positively correlates with HOMA‐IR and BMI in individuals with diabetes." (PMID 38718275, 2024). "However, the findings of the study unveiled that individuals diagnosed with T2DM exhibited increased levels of IL-6, and tumor necrosis factor alpha (TNF-α) in comparison to those without diabetes." (PMID 39408157, 2024). "The negative association between TNF-α and PD-1 expression on CD3+/CD4+ T cells further supports the notion that diabetes-induced immune alterations could diminish the T cell response, potentially exacerbating viral infections." (PMID 39456722, 2024). "Notably, the pro-inflammatory markers C-reactive protein (CRP), interleukin-1β (IL-1β), interleukin-6 (IL-6), NF-kB, and tumor necrosis factor-alpha (TNF-α) contribute to the chronic inflammatory state of T2DM and are significantly elevated in patients with diabetes." (PMID 39062550, 2024).
diabetes (continued). "Our list reports three tumor necrosis factor (TNF) inhibitors (HUMIRA, ENBREL, and REMICADE), two Janus kinase (JAK) inhibitors (RINVOQ, XELJANZ XR), two immune system modulators (COSENTYX, VEDOLIZUMAB), a lipid-lowering drug (ALLI), and a diabetes-lowering drug (TRULICITY)." (PMID 39764463, 2024). "In addition, the proteomic and genomic analysis in plasma and vascular bypass tissue of CHD patients without comorbidities or with the comorbidities hypertension and/or hypertension + diabetes identified some key mediators of CD40(L)–TRAF signaling, centered around TNFα." (PMID 38554187, 2024). "Therefore, we assessed in our rat model of diabetes-induced LEAD femoral artery tissue, levels of AGEs, ET-1, iNOS, and eNOS, and blood levels of TNF-α and biomarkers of dyslipidemia (TG, CHOL, LDL-C, and HDL-C) and glycemia (glucose and HbA1c) with and without metformin treatment." (PMID 36830898, 2023). "It was observed that anti-TNFα treatment did not prevent the development of diabetes." (PMID 37483613, 2023). "Therefore, it was not surprising to notice better diabetes control after the significant declines in TNFα, IL-6, and LTB4 levels in the montelukast group compared to the placebo." (PMID 37113754, 2023). "In the present study, we found that SDE alleviates IL-6, IL-8, and MCP-1 levels, and we also found that SDE alleviates TNF-α expression, which was commonly observed in DR tissues These results indicate that SDE may be a potential therapeutic agent for diabetes mellitus treatment." (PMID 37139437, 2023). "This comparison demonstrated that diabetes may lead to an increase in the levels of IL-2 and TNF-α without altering the levels of IL-4, IL-5, and INF-ɣ (p>0.05)." (PMID 37842429, 2023). "Vinores’ group investigated streptozotocin (STZ)-treated mice and Ins2Akita/+ mice with a TNF-α knockout, showing that there was a reduction in leucostasis by 1–2 weeks of diabetes, but TNF-α does not affect blood–retina barrier breakdown or CC3 levels until 3 months of development." (PMID 37670018, 2023). "In studies of type 1 diabetes mellitus (T1DM) mouse models, exogenous supplementation of C-peptide was found to aid in the reduction of pro-inflammatory cytokines such as IL17 and tumor necrosis factor-alpha (TNFα), and anti-inflammatory cytokines, like IL4 and IL10, in the urine (P <0.05)." (PMID 37745697, 2023). "Also, the hyperglycemic guinea pigs showed a rise in tumor necrosis factor (TNF) alpha and IL-1 beta along with elevated bacterial load, which was thought to be the reason for the failure of antitubercular treatment (ATT) in TB patients with diabetes." (PMID 36514631, 2022). "The synergistic effect of Cynara cardunculus and Citrus bergamia extracts has also been shown to be effective in lowering liver fat content, body weight, transaminases, lipids, oxidative stress and inflammatory biomarkers as TNF-α levels individuals with or without diabetes and NALFD." (PMID 35986358, 2022). "In addition, the injection of nondiabetic plasma-treated SVFs not only repressed the expression of the diabetes-induced ICAM, FMO3, IL-6, IL-1β, iNOS, TNF-α, and DPP4 expression, but also suppressed the phosphorylation of JNK and NF-κB in the liver of diabetic mice." (PMID 35883204, 2022). "Also, the relationship between age and IL-1β, IL-6, or TNFα production was not seen in this population compared to the healthy subjects, arguing that the presence of diabetes supersedes the impact of age." (PMID 36337734, 2022). "In addition, PISA showed a strong correlation with HbA1c, hs-CRP, and TNF-α, suggesting that PISA may be an effective index for evaluating periodontal disease and diabetic status in patients with diabetes and periodontal disease." (PMID 36140045, 2022).
diabetes (continued). "However, TNF-α, IL-1B, and IL-6 secretion in DD group was significantly enhanced than that in depression and diabetes group (P < 0.05, P < 0.01); CX3CR1 blocker treatment of DD group significantly reduced the levels of TNF-α, IL-1B, and IL-6 in hippocampus of all groups (P < 0.05, P < 0.01)." (PMID 36072409, 2022). "Previous studies have reported that increased secretion of tumor necrosis factor α (TNFα), interleukin (IL)-6, C-reactive protein (CRP), and other substances at low concentrations lead to chronic low-grade inflammatory responses accompanied by the development and progression of diabetes mellitus." (PMID 35062863, 2022). "Circulating levels of acute-phase proteins are elevated in diabetes, such as serum amyloid A, C-reactive protein (CRP), fibrinogen, haptoglobin, plasminogen activator inhibitor, sialic acid, interleukin (IL)-1β, IL-1 receptor antagonist (IL-1Ra), IL-6 and tumor necrosis factor (TNF)-α." (PMID 35327468, 2022). "In summary, this research revealed significant variations of adiponectin, nesfatin-1, IL-6, and TNF-α levels in the healthy, prediabetes, and T2DM, suggesting a significant but slow and gradual change during the progression from a healthy condition toward diabetes via prediabetes." (PMID 35311231, 2022). "The variation and correlation among adiponectin, nesfatin-1, tumor necrosis factor α (TNF-α), and interleukin 6 (IL-6), which may be involved in the development of the decline of health into prediabetes and diabetes, have not been elucidated." (PMID 35311231, 2022). "Diabetes increased TLR4-mediated inflammation, whereas DP inhibited the protein expression of the TLR4 pathway (TLR4, Myd88, IRAK1, and TRAF6) and reduced the mRNA expressions of IL-1β, IL-1α, IL-6, and TNF-α and the protein expressions of TNF-α, IL-1β, and COX-2." (PMID 35463063, 2022). "Cumulative evidence suggests that the upregulation of inflammatory factors such as tumor necrosis factor-α (TNF-α), intercellular adhesion molecule-1 (ICAM-1) and monocyte chemoattractant factor-1 (MCP-1 or CCL2), and subsequent leukocyte diapedesis, contribute to the BRB breakdown in diabetes." (PMID 34200613, 2021). "In people without diabetes SRA1 expression was associated with CCL3 (r = 0.298, p = 0.036), CCL8 (r = 0.344, p = 0.021), CXCL11 (r = 0.400, p = 0.003), TNF-α (r = 0.317, p = 0.030), TGF-β (r = 0.514, p < 0.0001), IL13 (r = 0.310, p = 0.028), and IL18 (r = 0.547, p < 0.0001)." (PMID 34685582, 2021). "Of interest, diabetes progress in TNFα-transgenic NOD mice is CD8+, but not CD4+, T cell dependent." (PMID 34778464, 2021). "The macroalbuminuria patients exhibited higher plasma levels of ANP, TNF-α, IL-6, and ADP; higher serum creatinine (Cr) and blood urea nitrogen (BUN); and longer duration of diabetes mellitus (DM) than the patients with normoalbuminuria and microalbuminuria." (PMID 34663293, 2021). "In addition, a clinical cohort study revealed rather specific negative correlations between the serum sitosterol level and the serum IL6 and TNF-α levels in both subjects with and without diabetes, suggesting the anti-inflammatory potential of β-sitosterol." (PMID 33953784, 2021). "Notably, according to animal studies, inflammatory markers such as TNF‐α and IL6 were significantly increased in diabetic mice model, indicating that diabetes could directly result in accelerating inflammation." (PMID 33694276, 2021). "In the current study, we demonstrated that mediators of diabetes such as HG and AGE modulate HREC-barrier function, cell-junction protein turnover, their intracellular distribution, and phosphorylation of Akt and P38 MAPK differently compared to treatment with bacterial LPS and TNFα." (PMID 35054426, 2021). "In the diabetics, the number of TNFα gold labels is significantly increased in the duodenum, decreased in the colon and remained unchanged in the ileal ganglia, while insulin does not prevent these diabetes-related TNFα changes." (PMID 34572059, 2021).
diabetes (continued). "In the colon, diabetes-related induction of the HO system and an elevated number of HO1-immunoreactive myenteric neurons was demonstrated, which may contribute to the decrease in TNFα expression in ganglia of this gut segment." (PMID 34572059, 2021). "In this study, we first presented markedly elevated Th1 cytokine IL-2R and TNF-α levels and increased levels of Th2 cytokines, including IL-6, IL-8, and IL-10, in patients with diabetes compared with patients without diabetes among patients with COVID-19 pneumonia." (PMID 33776910, 2021). "Moreover, many clinical studies have found that both serum and urinary levels of TNF in patients with DN are higher than in nondiabetic individuals, and also higher than in patients with diabetes who have no kidney involvement." (PMID 34411124, 2021). "However, on the 14th day, nanofiber dressing groups had significantly lower levels of TNF-α than the control diabetes group, with doxycycline dressings, in comparison with non-doxycycline dressings, leading to a greater reduction in TNF-α concentration." (PMID 33841538, 2020). "However, the absence of TNF-α significantly suppressed BRB breakdown in 6-month-old mice with diabetes." (PMID 33013692, 2020). "Moreover, vegetable intake was negatively associated with serum levels of C-reactive protein, IL-6, and TNF-α in healthy individuals without cardiovascular disease or diabetes mellitus." (PMID 33171846, 2020). "However, to our knowledge, no clinical studies are targeting TNF-α in the context of renal complications of diabetes." (PMID 32471207, 2020). "In healthy population and in those with different chronic diseases like diabetes, atherosclerosis and polyarthritis, the higher concentrations of 25(OH)D have been correlated with lower status of inflammatory biomarkers including interleukin 6, CRP, and tumor necrosis factor alpha." (PMID 30791895, 2019). "Both the spinal cord TNF-α and CXCR4 protein expressions were significantly increased at 5 weeks (P < 0.05) but not at 2 weeks of diabetes (P > 0.05, diabetes vs. control) despite significant reductions in the thresholds of PWT and PWL as early as 1 week of diabetes as compared to control." (PMID 31001066, 2019). "Using advanced stem cell characterization techniques, we could also demonstrate that metabolic disease such as diabetes mellitus represses expression of Indian Hedgehog (IHH) in SSCs, vested on high exposure of circulating tumor necrosis factor-alpha (TNFα), impairing bone repair." (PMID 31572721, 2019). "By contrast, diabetes did not induce serum TNF levels before the septic challenge." (PMID 29780390, 2018). "However, a chronic increase in inflammatory markers, such as interleukin (IL)-6, IL-1, tumor necrosis factor α (TNF-α), and C-reactive protein (CRP), plays a key role in various chronic conditions (e.g., type 2 diabetes mellitus [T2DM], cardiovascular diseases [CVDs], and cancer)." (PMID 29495330, 2018). "Diabetes in this case becomes a confounding factor, in that it establishes a low-grade inflammatory state, characterized by elevated levels of acute phase reactants such as CRP, interleukin-6 (IL-6), secretory phospholipase A2 and tumor necrosis factor alpha (TNFα)." (PMID 29547660, 2018). "Finally, liposomal formulation of citicoline was able to ameliorate the overexpression TNF-α, but not of IL-1β, induced by diabetes." (PMID 30127248, 2018). "HF animals presented neither diabetes nor hypertension and only a mild elevation in the proinflammatory cytokines IL-6 and TNF-α in serum, that, in spite of non-significant may be indicative of ongoing systemic inflammation process." (PMID 28358868, 2017). "Interestingly, treatment with LPLI decreases the diabetes-induced transcription of HMGB1 and RAGE, with reductions of AGE, RAGE, HMGB1 and TNF-α protein expression, possibly down-regulating NF-κB in diabetic SMGs, indicating that LPLI has a potent anti-inflammatory effect." (PMID 28099448, 2017).
diabetes (continued). "However, AS-IV dose-dependently suppressed diabetes-induced MCP-1 and TNF-α upregulation." (PMID 28761152, 2017). "In patients with type 2 diabetes mellitus or metabolic syndrome, neutralization of circulating TNF-α does not improve insulin sensitivity because the elevated TNF-α levels are a homeostatic response to maintain cytoplasmic glycogen in myocytes, not driven by inflammation." (PMID 29435395, 2017). "However, whether TNF-α stimulates osteocytic RANKL and sclerostin expressions in diabetes with periodontitis is currently unclear." (PMID 29240821, 2017). "However, the involvement of IL-1β and TNF-α of Kupffer cells in diabetes-enhanced liver abscess has not been clarified." (PMID 28493939, 2017). "Seventeen patients with type 2 diabetes mellitus under clinical management weresubmitted to surgery and blood samples were collected before and six months aftersurgery for evaluation of the serum profile of proinflammatory (IFN-γ, TNF-α,IL-17A) and anti-inflammatory cytokines (IL-4, IL-10)." (PMID 26734798, 2015). "Individual cytokine blockers might possess unique properties in modulating brain function; for example, IL-1 blockade leads to improvement of fatigue in patients with Sjögren’s syndrome and diabetes mellitus, whereas TNF blockade does not." (PMID 26477946, 2015). "TNFα is first synthesized as a transmembrane protein and then is turned into is soluble form through the cleavage by ADAM-17 (A disintegrin A metalloproteinase 17), which increased activity is related to ischemia, heart failure, atherosclerosis, diabetes and hypertension." (PMID 26578976, 2015). "Similarly to TNF-α, IL-6 levels are also higher in patients with DN in comparison with diabetes mellitus patients without nephropathy." (PMID 25785280, 2015). "Factors included in the multivariate analysis were age, duration of diabetes, BMI, SBP, history of cardiovascular disease, presence of retinopathy, hypertension, glycosylated haemoglobin levels, treatment with clopidogrel, ACEi/ARBs, and eGFR and urinary TNF-α excretion." (PMID 25587544, 2014). "Diabetes results in a marked increase in the expression of ICAM-1, VEGF, and TNF-α, whereas MALAT1 knockdown could significantly reduce the induction of VEGF, TNF-α, and ICAM-1, suggesting that MALAT1 knockdown could alleviate retinal inflammation in diabetic rats." (PMID 25356875, 2014). "WP suppresses TNF-α production, which is the key factor in ß cell-destruction in T1D since TNF-α controls the expression of the inflammatory gene network and contributes to the pathological complications observed in many inflammatory diseases such as schizophrenia and diabetes." (PMID 25009576, 2014). "Some of the negative effects of diabetes-enhanced TNF on wound healing may be due to the impact of the FOXO1 transcription factor." (PMID 23484152, 2013). "In conclusion, the present study shows that previous diabetes induction in vivo negatively regulated SIRT1 amounts in rat VSMCs, consistent with the in vitro effects of high glucose concentrations, whereas we were unable to demonstrate SIRT1 modulation by TNF-α." (PMID 23734259, 2013). "Other cytokines including TNFα, IL-10, and IL-12 did not change with diabetes control." (PMID 22924123, 2012). "Indeed anti-TNF-α has been reported to prevent diabetes but not restore euglycemia in overtly diabetic NODs." (PMID 22606220, 2012). "The levels of circulating proinflammatory cytokines and chemokines such as tumor necrosis factor-α (TNF-α), interleukin-1β (IL-1β), and monocyte chemoattractant protein-1 (MCP-1) are commonly used as markers of inflammation, and they have been shown to be increased in diabetes." (PMID 23316106, 2012). "ARBs also have anti-inflammatory effects as seen by lowering effect on plasma TNF-α and IL-6 levels in patients with diabetes and hypertension Telmisartan, but not valsartan, was shown to attenuate TNF-α induced IL-6 production by vascular smooth muscle cells in a PPAR-γ dependent manner." (PMID 21276223, 2011).